CD47 (CD47 molecule)
Diseases named in the same sentence as CD47 in open-access papers (continued):
Sharing a sentence is not in itself a finding about the gene and the disease.
breast carcinoma (continued). "In this study, breast cancer cell lines with combinations of estrogen receptor (ER), progesterone receptor (PR), and human epidermal growth factor receptor (HER2) biomarkers as well as triple negative cell lines were interrogated for CD47 expression." (PMID 30463284, 2018). "Our results showed that all the breast cancer cell lines overexpressed CD47 to a significant degree regardless of their expression of ER, PR, or HER2." (PMID 30463284, 2018). "Notice the specific binding of our CD47 targeted nanoparticles to the breast cancer specimen as opposed to our isotype labeled nanoparticles." (PMID 30463284, 2018). "Altogether, these results suggested that expressions of both MYC and CD47 were positively regulated by MALAT1 in triple negative and Her-2 positive breast cancers, which implied that MALAT1 might get involved in immune escape of breast cancer cells." (PMID 29416769, 2018). "Moreover, GRP78 knockdown reduced the amount of CD47 on the cell surface in LCC1 and LCC9 cell lines versus controls (transfected breast cancer cells)." (PMID 28815041, 2017). "Moreover, the CD47 increase was greatest in the MCF7 breast cancer cell line compared to other lines, even though MCF7 cells already express high CD47 levels." (PMID 28378740, 2017). "Co-incubation with TNF-α for 48 h led to a significant increase in CD47 expression on MCF7 breast cancer cells (already CD47Hi) but only a slight increase on nontumorigenic breast cancer MCF10 cells (CD47Med) and the hepatoma cancer cell line HepG2 (CD47Lo)." (PMID 28378740, 2017). "Our new data generated in LCC1 (tamoxifen-sensitive breast cancer cells) and LCC9 (tamoxifen-resistant breast cancer cells) indicate that CD47 expression is increased in LCC9 cells, showing for the first time that CD47 expression correlates with resistance to anti-estrogen therapy." (PMID 28815041, 2017). "Thus, we believe that activation of SEs is a mechanism used by certain cancers, such as breast cancer, T-ALL and DLBCL, to obtain high CD47 levels." (PMID 28378740, 2017). "By rank-ordering of enhancer regions based on H3K27ac enrichment, we discovered that T-cell acute lymphoblastic leukemia (T-ALL (RPMI18402, Jurkat and MOLT3)) diffuse large B-cell lymphoma (DLBCL (LY4)) and breast cancer (MCF7 and HCC1954) cell lines have SEs within ∼200 kb of CD47." (PMID 28378740, 2017). "Because elevated miR-7 expression was reported to inhibit proliferation and induce apoptosis of breast cancer cells, the induction of miR-7 in bCSC by B6H12 may also contribute to the observed inhibition of bCSC proliferation by this CD47 antibody." (PMID 26840086, 2016). "Indeed, TSP-1 is down-regulated in taxane resistant cells due to its ability to induce apoptosis via CD47 ligation, and TSP-1 binding to CD47 is also recognized to induce killing of breast cancer cells." (PMID 26046793, 2015). "Therapeutic strategies targeting TAMs in breast cancer have evolved from depletion approaches (CSF1/CSF1R blockade) to inhibition of monocyte recruitment (CCL2/CCR2 axis), functional reprogramming (CD40 agonism, PI3Kγ inhibition), and macrophage-directed checkpoint modulation (CD47-SIRPα axis)." (PMID 42122206, 2026). "In some tissue samples clinically proven to be inflammation rather than breast cancer samples (J07), expression of integrin αvβ3+ (520 nm green fluorescence) or CD47+ (570 nm red fluorescence) was observed, with no appreciable colocalization around the nucleus." (PMID 41168993, 2026). "Analysis of genes that are induced by HIFs in breast cancer and promote immune evasion revealed that CD47 and CD73 were not induced in hypoxic Hepa1-6 cells, whereas PDL1 mRNA was induced in vehicle-treated but not in 32-134D–treated cells under hypoxic conditions." (PMID 35499076, 2022). "Thus, CD47 signaling limits stem cell character in non-transformed cells but is necessary to maintain stem cell characteristics in breast cancer stem cells." (PMID 33925464, 2021).
breast carcinoma (continued). "We also found that CD47 and CD68 expression were more abundant in hormone receptor-negative breast cancer, such as triple-negative breast cancer (TNBC) and HER2 overexpression breast cancer, while the expression density of CD47 and CD68 decreased in luminal-type breast cancer." (PMID 31528120, 2019). "Our study showed for the first time that combined high expression of CD47 and CD68 represented an even better independent predictor for poor prognosis compared to the expression of CD47 or CD68 alone, and could be a novel prognostic factor for breast cancer patients." (PMID 31528120, 2019). "Interestingly, MET was suggested to contribute to the putative metastasis-initiator circulating cells in breast cancer (e.g. EPCAM+CD44+CD47+MET+ CTCs, but not the bulk EPCAM+ CTCs)." (PMID 28212540, 2017). "Flow cytometry analyses showed that TNFR1 expression levels were higher on the surface of the MCF7 cancer line than on MCF10 (a breast cancer cell line not considered tumorigenic) and the HepG2 (hepatoma) cancer line, which natively expresses low levels of CD47." (PMID 28378740, 2017). "Our data and recent reports that shRNA knockdown of CD47 suppressed CSCs in hepatocellular carcinoma and mammospheres formation in the SUM159 breast carcinoma cell line suggest that direct cell-autonomous effects of therapeutic CD47 antibodies to suppress CSC may extend to additional cancers." (PMID 26840086, 2016). "Similarly, the supramolecule blocking the CD47-SIRPα signaling axis while sustainably inhibiting CSF-1R enhanced M2 to M1 repolarization within the TME and significantly improved antitumor and antimetastatic efficacies in animal models of melanoma and breast cancer." (PMID 31779710, 2019). "High expression of CD47 correlates with worse survival in both HR+ and HER2+ breast cancer but not TNBC." (PMID 34135901, 2021). "Our study also confirmed the first time that the prognostic significance of combined high expression of CD47 and CD68 not only in breast cancer in general, but also in hormone receptor-negative breast cancer in particular." (PMID 31528120, 2019). "The exact role of CD47 and CD68 in breast cancer, especially in hormone receptor-negative breast cancer, still needs to be evaluated in follow-up mechanistic investigations." (PMID 31528120, 2019). "In this study, analyses of H3K27ac enrichment around the CD47 locus indicated that SEs are present in T-ALL and breast cancer cells but not in their normal counterparts, CD3+ T cells and human mammary epithelium." (PMID 28378740, 2017). "Breast carcinomas and uveal melanoma also showed significant correlations between higher IFT57 expression above the mean and improved overall survival that were not significant for CD47." (PMID 39201643, 2024). "Moreover, the prognostic significance of combined high expression of CD47 and CD68 not only in breast cancer in general, but also in hormone receptor-negative breast cancer in particular." (PMID 31528120, 2019). "Combined detection of CD47 and CD68 may provide guidance for the prognosis of breast cancer, especially hormone receptor-negative breast cancer." (PMID 31528120, 2019). "The addition of CD47 to this SERS nanoparticle cocktail could have beneficial effects, especially in cases where breast cancer patients do not express HER2 or ER." (PMID 30463284, 2018). "In contrast to the differential CD47 expression profiles, we did not observe a significant difference of CD44 protein levels between the exosomes from the healthy control group and those from the breast cancer patients." (PMID 27819324, 2016).
anemia (149 papers, 2013 to 2026). A reduction in the number of red blood cells, the amount of hemoglobin, and/or the volume of packed red blood cells. "In the current study, we demonstrate that maplirpacept also has limited binding to RBCs; potentially reducing the risk for phagocytic anemia that is associated with anti-CD47 mAb approaches." (PMID 40078999, 2025). "Anti-CD47 strategies have shown promising results in several cancers, but have also faced important limitations, such as anemia caused by widespread CD47 expression, spanning to erythroid cells." (PMID 40373279, 2025). "Second humanized monoclonal antibody, lemzoparlimab, binds a distinct CD47 epitope, reducing epitope, reducing cell affinity and anemia risk." (PMID 41303525, 2025). "Although promising, given that the broad expression of CD47 in healthy cells, systemic infusion of CD47 inhibitors can cause the limited efficacy and adverse effects such as anemia." (PMID 38890636, 2024). "This differs from antibody treatments targeting CD47, which can cause anemia due to the expression of CD47 on RBCs." (PMID 38319147, 2024). "The persistent obstacles of toxicities pose ongoing challenges, with hematotoxicity, particularly anemia, and off-target myelosuppression emerging as predominant AEs associated with CD47 inhibitors." (PMID 39040441, 2024). "Mice with mutations that promote diabetes and that lack CD47 developed anaemia sooner and to a more severe degree than CD47‐positive mice, a fact taken as showing that CD47 was tolerant." (PMID 38362603, 2024). "CD47 is critical to red blood cell homeostasis and targeting CD47 can potentially cause an ‘on-target off-tumor’ adverse effect of anemia." (PMID 38322418, 2024). "CD47 antibody therapy has been associated with hematotoxicity, particularly anemia, due to expression of CD47 on red blood cells." (PMID 39545414, 2024). "Although anemia was a frequent side effect of anti-CD47 therapy, risk-mitigation strategies such as using a low “priming” dose have significantly decreased this risk in clinical studies." (PMID 39040441, 2024). "The CD47 mAb Magrolimab is initially administered using a priming dose to deplete aged RBCs susceptible to phagocytic clearance induced by CD47 blockade to avoid anemia during maintenance dosing." (PMID 37958404, 2023). "CD47 blockade can cause anemia and other hematological toxicities due to the phagocytosis of healthy red blood cells, which express CD47 as a “don’t eat me” signal to prevent their destruction by macrophages in the spleen and liver." (PMID 38188674, 2023). "Unsurprisingly, the free aCD47 treatment caused anemia in 60% (3/5) of the mice due to CD47 overexpression on the red blood cell membrane." (PMID 37132609, 2023). "Anemia and thrombocytopenia are the most common adverse events (AEs) associated with CD47 monoclonal antibodies." (PMID 36726125, 2023). "This ‘regain-of-function’ improves the clearance of cancer cells but also leads to unwanted removal of the anti-CD47-sensitive normal cells such as erythrocytes or platelets, causing transient anemia or thrombocytopenia in treated patients." (PMID 35664753, 2022). "Anti-CD47 mAbs were significantly more likely than selective SIRPα blockers to cause grade 1-2 fever, chills, nausea/vomiting, headache, and anemia." (PMID 36439116, 2022). "SIRPα variants encapsulated by exosomes were less likely to cause anemia and exhibited milder hematotoxicity than naked SIRPα variants and CD47 antibodies." (PMID 36435797, 2022). "Although magrolimab is generally well-tolerated in human clinical trials, anemia caused by on-target off-tumor binding of CD47 expressed on erythrocytes was a common treatment-related side effect." (PMID 33790906, 2021). "CD47 inhibition can cause anemia and infections are more common in patients treated with the IL-6 antibody tocilizumab." (PMID 32814713, 2020).
anemia (continued). "CD47 deficiency is associated with development of anemia as a result of increased susceptibility of CD47−/− RBC to phagocytosis under pathological circumstances." (PMID 28018860, 2016). "It has been suggested that the anemia associated with the untreated disease can in part be explained by a combination of reduced CD47 levels together with other morphological erythrocyte abnormalities observed in this disease." (PMID 23401787, 2013). "However, the clinical application of early CD47 antibodies has been associated with significant hematotoxicities, including hemagglutination, anemia, and thrombopenia." (PMID 41383500, 2025). "As CD47 also exists in healthy cells, anti-CD47 antibodies may damage these cells and cause potential off-target effects, such as anemia, thrombocytopenia and leukopenia; thus, limiting clinical use." (PMID 40296909, 2025). "We hypothesized that expression of human CD47 would mitigate the loss of mouse RBCs and reduce anemia." (PMID 40956886, 2025). "However, the expression of CD47 in a wide range of cells poses a challenge, as CD47 monoclonal antibodies can bind to red blood cells, causing severe anemia." (PMID 40055311, 2025). "Systemic inhibition of CD47 poses a risk of anemia due to the clearance of erythrocytes." (PMID 41590849, 2025). "However, due to the high expression of CD47 in human red blood cells and platelets, blocking CD47 causes side effects such as severe anemia and thrombocytopenia, which greatly limits the clinical development of such therapeutics." (PMID 38168654, 2024). "Low high density lipoprotein (HDL) has frequently been associated with untreated CD47, and the combination of unexplained iron-deficiency anemia and low HDL may be particularly suggestive of CD48." (PMID 39730479, 2024). "Moreover, CD47 blockade is associated with substantial adverse effects, most notably anemia, since CD47 is widely expressed in healthy cells, especially in red blood cells (RBCs)." (PMID 37345054, 2023). "Given the widespread expression of CD47, anti-CD47 antibodies may cause serious side effects such as anemia, thrombocytopenia, and leukopenia, as observed in animal models." (PMID 37670322, 2023). "The local delivery of oAd-mCD47nb-Fc bypasses the neutralizing antibodies present in the circulatory system and increases the intratumoral concentration of the agents, avoiding severe anemia caused by the systemic administration of anti-CD47 monoclonal antibodies." (PMID 35837100, 2022). "However, M2-type macrophages restrict the efficacy of CD47 antagonists and CD47 antagonists would cause serious anemia and thrombocytopenia." (PMID 35524277, 2022). "However, CD47 is a ubiquitously expressed cell surface protein also found on red blood cells and antibodies against CD47 have been associated with adverse events including anaemia." (PMID 36551637, 2022). "Furthermore, treatment is associated with severe side effects, most notably anaemia, that are attributable to the ubiquitous expression of CD47." (PMID 35908284, 2022). "If targeting CD47 causes thrombocytopenia and anemia, what about targeting SIRPα?" (PMID 36429020, 2022). "As a result of the ubiquitous expression and unique properties of CD47, more attention is now principally being focused on haematotoxicity, including anaemia and thrombocytopenia, caused by the administration of anti‐CD47 blocking antibodies in clinical oncology studies." (PMID 33449453, 2021). "Among the anti-CD47 mAbs, many have the differentiated characteristics of binding to CD47 with high affinity, and minimal binding to human erythrocytes, which reduces the potential adverse effect of anemia caused by HA." (PMID 34717705, 2021). "However, CD47 targeting causes anemia and thrombocytopenia due to the high CD47 expression on red blood cells and platelets." (PMID 32260071, 2020). "However, therapeutic antibodies targeting CD47 in the clinical stage would result in the on-target risk of anemia and hemagglutination." (PMID 31931812, 2020).
anemia (continued). "CD47 is, however, expressed at high levels in red blood cells (RBCs), and undesirable anemia caused by CD47-blocking antibody-induced phagocytosis of RBCs may complicate anti-CD47 cancer therapy." (PMID 28883531, 2017). "However, anti-CD47 antibodies also causes anemia owing to inappropriate clearance of red blood cells." (PMID 29379788, 2017). "Thus, if on one hand RBC clearance promoted by the absence of CD47 attenuates malaria parasitemia (pRBC), on the other hand it leads to anemia (nRBC), as observed in CD47-deficient mice with P. berghei malaria." (PMID 28018860, 2016). "CD47 blockers promote macrophage uptake of apoptotic cells after excessive blockade of CD47, which increases the cholesterol burden on macrophages, leading to the formation of cholesterol crystals (CCs) and CD47 blockers are currently associated with side effects such as anemia." (PMID 39852558, 2024). "Most importantly, the immunotherapy based on CD47 down-regulation may raise a concern about anemia because red blood cells also evade the macrophage phagocytosis response by high-expressed CD47, and the severe anemia caused by CD47 ICB therapy become a crucial issue for clinical usage in patients." (PMID 37951973, 2023). "However, targeting CD47 may bring side effects like anemia as red blood cells will be removed when CD47 is deficient in their surfaces." (PMID 37063864, 2023). "However, anemia, thrombocytopenia, and other adverse events caused by macrophage-mediated cellular phagocytosis limit the feasibility of the systemic administration of anti-CD47 agents." (PMID 35837100, 2022). "However, due to the broad expression of CD47, treatment with CD47-targeting agents have caused significant anemia and thrombocytopenia in both preclinical studies and clinical trials, and higher therapeutic doses of CD47-targeting agents are needed to overcome the antigen sink and block CD47." (PMID 35256517, 2022). "In a phase I trial, a humanized anti‐CD47 antibody decreased carotid artery inflammation, although anemia emerged as a side effect due to erythrophagocytosis of aged red blood cells." (PMID 41546123, 2026). "Although several CD47 antibodies have generally avoided hemagglutination, anemia, and thrombopenia remain, potentially mediated by enhanced phagocytosis of erythrocytes and thrombocytes." (PMID 41383500, 2025). "Anemia, which has been frequently observed with other CD47 blockers, only occurred in 25% of patients in this trial and was low-grade in all cases except one (co-occurring with HLH), consistent with evorpacept’s inactive Fc domain and prior data." (PMID 41171165, 2025). "Nevertheless, as CD47 is ubiquitously expressed on healthy cells, its targeting leads to CD47-induced toxicities, such as anemia and thrombocytopenia." (PMID 40402266, 2025). "A primary challenge associated with CD47‐targeted therapies is the potential for hematologic toxicity, including anaemia, thrombocytopenia, and leukopenia, due to the widespread expression of CD47 on normal erythrocytes and platelets." (PMID 41195773, 2025). "The early CD47-blocking mAb Hu5F9-G4 exhibited a high affinity for CD47 on erythrocytes and thrombocytes and encountered significant challenges in clinical development due to severe anemia and thrombopenia." (PMID 41383500, 2025). "Blocking CD47 or SIRPα promotes macrophage clearance of necHCs and reduces HSC activation (α-SMA, Col1a1); anti-SIRPα avoids anemia associated with CD47 blockade." (PMID 40630093, 2025). "The inactive Fc domain prevents antibody-dependent cellular phagocytosis of CD47-expressing hematopoietic cells, minimizing anemia." (PMID 41171165, 2025). "While CD47 blockade can mitigate tumor growth, many CD47 blockers also bind to red blood cells (RBCs), leading to anemia." (PMID 40078999, 2025). "Although blockade of the CD47-SIRPα axis is a promising immunotherapeutic strategy, clinical development has been hindered by on-target toxicities (e.g., severe anemia) and insufficient potency." (PMID 41131565, 2025).